RN7SL619P (RNA, 7SL, cytoplasmic 619, pseudogene)
Gene: Miscellaneous RNA gene on chromosome 19 (13,815,062 to 13,815,319, reverse strand). Ensembl gene ENSG00000266770.
Homologues: Orthologues: macaque Metazoa_SRP (71% identical). Paralogues in human: Metazoa_SRP (79% identical), RN7SL275P (78% identical), RN7SL744P (78% identical), Metazoa_SRP (76% identical), RN7SL376P (76% identical), RN7SL488P (72% identical), RN7SL560P (71% identical), RN7SL377P (70% identical), RN7SL339P (69% identical), RN7SL48P (68% identical), RN7SL644P (66% identical), Metazoa_SRP (62% identical), and 700 more.